SNORA63 (small nucleolar RNA, H/ACA box 63)
Synonyms: E3; E3-2; SNORA63A; RNE3; RNU107; elF-4AII
Gene: Small nucleolar RNA gene on chromosome 3 (186,787,300 to 186,787,431, forward strand). Ensembl gene ENSG00000200320.
Gene Ontology:
Biological process: RNA processing
Cellular component: nucleolus
Homologues: Orthologues: chimpanzee SNORA63 (100% identical), macaque SNORA63 (97% identical), dog SNORA63 (95% identical), pig SNORA63 (95% identical), guinea pig SNORA63 (92% identical), mouse Gm26447 (91% identical), rabbit SNORA63 (91% identical), rat LOC120095726 (89% identical). Paralogues in human: SNORA63 (92% identical), SNORA63C (90% identical), SNORA63E (77% identical), SNORA63D (74% identical), SNORA63B (68% identical), SNORA63 (62% identical), SNORA63 (59% identical), SNORA63 (46% identical).
Diseases named in the same sentence as SNORA63 in open-access papers:
SNORA63 is named in the same sentence as 2 diseases in open-access papers, as found by Europe PMC text mining. Sharing a sentence is not in itself a finding about the gene and the disease.
SNORA63 shares sentences with these, for which no sentence is quoted: cancer (1 paper); mastitis (1).